MUC2 (mucin 2, oligomeric mucus/gel-forming)
Diseases named in the same sentence as MUC2 in open-access papers (continued):
Sharing a sentence is not in itself a finding about the gene and the disease.
cholangiocarcinoma (7 papers, 2006 to 2024). A carcinoma that arises from the intrahepatic biliary tree (intrahepatic cholangiocarcinoma) or from the junction, or adjacent to the junction, of the right and left hepatic ducts (hilar cholangiocarcinoma). "In contrast, MUC2, an intestinal-type mucin that is selectively expressed predominantly in well-differentiated and noninvasive mucinous-type intraductal cholangiocarcinomas with gastrointestinal differentiation, predicts a more favourable prognosis." (PMID 27933122, 2009). "TH, IGDCC3, RAD51AP2, and MUC2 are genes that were identified by WGCNA and are related to the clinical prognosis and survival of cholangiocarcinoma, but they have already been reported." (PMID 36979826, 2023). "MUC1 showed high expression in cholangiocarcinomas and cholangiocellular differentiated areas of cHCC-CCC, whereas MUC2, MUC3, MUC5/6, MUC5AC, MUC6, and MUC7 showed limited usefulness for further differentiation." (PMID 36672443, 2023).
cystic fibrosis (7 papers, 2011 to 2025). Autosomal recessive disorder caused by pathogenic variants in the CFTR gene (cystic fibrosis transmembrane conductance regulator), which encodes a chloride and bicarbonate channel expressed in epithelial cells, and follow the diagnosis criteria. "In addition to Muc5ac, Muc2 is also associated with inflammatory airway diseases such as chronic bronchitis, and cystic fibrosis." (PMID 26084512, 2015). "Pseudomonas aeruginosa, a common Cystic fibrosis pathogen, activates MUC2 mucin gene transcription by activation of a Src-dependent Ras-MEK1/2-ERK1/2-pp90rsk-NF-κB pathway." (PMID 22073249, 2011).
dysplasia (7 papers, 2014 to 2024). A usually neoplastic transformation of the cell, associated with altered architectural tissue patterns. "MUC2 was reduced in 8.2% (5/61) of LGD or lost in 11.1% (4/33) of EAC, while TFF3 was positive in all GCs of BE and BE-associated dysplasia." (PMID 39001449, 2024). "Gastric intestinal metaplasia is a common complication for H. pylori-induced metaplasia-dysplasia-carcinoma sequence, which was characterized by increased CDX2 and/or MUC2 expression, which has been received PPI treatment." (PMID 39575386, 2024). "Specifically, during normal esophageal squamous, BE metaplasia, dysplasia, and EAC progression there is a progressive increase in TFF2, TFF3, MUC2, MUC5AC, MUC6, CDX2 with the development of intestinal metaplasia." (PMID 36994101, 2023). "We performed immunostaining for β-catenin, MLH1, and mucins (e.g., MUC2, MUC5AC, MUC6, and CD10); targeted next-generation sequencing; and microsatellite instability (MSI) testing in 8 SSA/P lesions comprised of 4 SSA/Ps with high-grade dysplasia and 4 SSA/Ps with submucosal carcinoma." (PMID 30458818, 2018). "Specifically, quantification of triple immunofluorescence staining of eight BO EMR specimens with intestinal metaplasia but no dysplasia taken from five patients showed 41% of MUC2 low cells expressed SPINK4 and/or ITLN1, whereas 28% of cells expressed MUC2 alone." (PMID 30323168, 2018). "In 30 BO endoscopic mucosal resection (EMR) specimens (from 16 patients) with intestinal metaplasia but no dysplasia present, we also consistently observed cells expressing ITLN1 or SPINK4 without MUC2." (PMID 30323168, 2018).
endometriosis (7 papers, 2012 to 2025). The growth of functional endometrial tissue in anatomic sites outside the uterine body. "The aim of this study was to investigate the possible association of MUC2 gene polymorphisms with the risk of endometriosis and endometriosis-related clinical symptoms in a Taiwanese population." (PMID 22417007, 2012). "In this study, our data revealed a significant association between MUC2 polymorphisms and endometriosis in a Taiwanese population." (PMID 22417007, 2012). "One of the endometriosis-associated SNPs (rs10902088) in MUC2 gene caused an amino acid substitution, and functions of MUC2 might be altered if such substitution changes surface charge, protein stability or folding." (PMID 22417007, 2012). "Comparative analysis of WES data from RPL patients and healthy controls identified polymorphisms in the proprotein convertase subtilisin/kexin type 5 (PCSK5) and mucin 2 (MUC2) genes, both previously reported in association with endometriosis." (PMID 40724834, 2025). "MUC2 expression was reported to be regulated by many endometriosis-related cytokines, such as IL-1β, IL-6, TNF-α, NF-Kappa B." (PMID 22417007, 2012). "Although the PCSK5 and MUC2 genes have previously been implicated in endometriosis, their involvement in pregnancy loss has not been well characterized." (PMID 40724834, 2025). "Because endometriosis was suggested as one source of female infertility, we asked whether genetic variations in MUC2 play roles in this process." (PMID 22417007, 2012). "However, there has been no study yet investigating the relationship between endometriosis and MUC2, while previous functional studies on MUC2 are more focused on its role in the gastrointestinal and respiratory tract." (PMID 22417007, 2012).
intestinal cancer (7 papers, 2013 to 2025). "Immunostaining showed that intestinal cancer markers (MUC2 and CHGA) and proliferation marker (Ki67) were highly expressed in metastatic tumors derived from orthotopic PDX liver cancers established with Liver ECM." (PMID 40852642, 2025).
intestinal tumors (7 papers, 2014 to 2023). "The role of MUC2 in defense against microbes has been confirmed in several experimental models in which MUC2 deficiency was correlated with reduced inner mucus layer, resulting in increased intestinal permeability and susceptibility to inflammation and intestinal tumors." (PMID 37402104, 2023). "However, studies in the literature have also indicated that MUC2 could suppress inflammation and inhibit the development of intestinal tumors, and that the loss of MUC2 expression was a predictor of adverse outcomes." (PMID 30922401, 2019). "100% of the MUC2−/− mice fed with normal diet developed intestinal tumors, but 5% or 10% dietary MBF significantly inhibited intestinal tumor formation, deceased tumor incidence to 20% and 30%, respectively." (PMID 26615818, 2015). "Intestinal tumor formation and cell proliferation was inhibited after a 12-week consumption of a Western-style diet supplemented with 10% (wt/wt) freeze-dried black raspberries in Apc1638+/− and Muc2−/− mice, both models of human colorectal cancer, although via distinct mechanisms." (PMID 27775562, 2016).
pancreatic ductal adenocarcinoma (7 papers, 2010 to 2025). An infiltrating adenocarcinoma that arises from the epithelial cells of the pancreas. "MUC2 has been found to be expressed mainly in the noninvasive tumors such as intraductal papillary mucinous neoplasm of the pancreas (IPMN) and mucin-producing bile duct tumor (MPBT), whereas MUC2 does not appear to be expressed in pancreatic ductal adenocarcinoma." (PMID 23101681, 2012). "Pancreatic ductal adenocarcinoma (PDAC) displays a typical mucin expression pattern which is characterized by MUC1 positive, MUC2 negative, and MUC5AC positive." (PMID 35910854, 2022).
pseudomyxoma peritonei (7 papers, 2008 to 2025). An appendix cancer that is characterized by progressive accumulation of mucus-secreting tumor cells within the abdomen and pelvis. "Relative chemoresistance of appendiceal pseudomyxoma peritonei (PMP) is attributed to abundant extracellular mucin 2 (MUC2) protein production." (PMID 29290997, 2017).
colorectal tumors (6 papers, 2010 to 2024). "Muc2 deficient mice spontaneously develop colonic adenoma that may degenerate into colorectal tumors." (PMID 24281201, 2010). "However, in some cases, decreased expression of secreted mucins (i.e. MUC2 and MUC5AC) is an indicator of more aggressive colorectal tumour, possibly because these cells are more dedifferentiated and thus more invasive." (PMID 35131032, 2022). "In addition, colorectal tumours that did not contain any MUC2+ cells still had an EPHB2-/ERBB3+ cell population (data not shown)." (PMID 26367378, 2015).
enterocolitis (6 papers, 2011 to 2025). An inflammatory process affecting the small intestine and colon. "MUC1 is often upregulated during enterocolitis and may contribute to epithelial proliferation and inflammation, while MUC2, secreted by goblet cells, is vital for maintaining the mucosal barrier and microbial homeostasis." (PMID 40431496, 2025). "Deficiency of fatty acid synthase (FASN) in the colonic epithelium blocks mucin 2 (MUC2) production, disrupts the intestinal barrier, and induces enterocolitis." (PMID 39465140, 2024). "Although some studies have yielded evidence that secretory mucins such as MUC2 may be induced as a result of inflammatory stimulation and that mice deficient in the MUC2 spontaneously develop enterocolitis, the same may not apply to the membrane-bound mucins like MUC4." (PMID 25949213, 2015).
infectious colitis (6 papers, 2010 to 2024). A viral or bacterial infectious process affecting the large intestine. "For example, muc2-/- mice are susceptible to chronic mucosal inflammation elicited by the normal gut flora and to lethal infectious colitis by Citrobacter rodentium." (PMID 21829463, 2011). "In infectious colitis and IBD, where MUC2 production is significantly increased, misfolded MUC2 accumulates, leading to ER stress-mediated goblet cell death." (PMID 36759578, 2023).
intestinal inflammation (6 papers, 2020 to 2025). "Mice deficient in Mucin 2 (Muc2), a gene encoding for the major mucus protein, develop spontaneous intestinal inflammation, probably as a result of the missing mucus layer and the prolonged contact between gut bacteria and intestinal epithelium." (PMID 34206809, 2021). "MUC2 knockout mice had greater intestinal inflammation and reduced body weight gain compared with MUC2-expressing mice, despite equal food intake, and exhibited intestinal microbiome, short chain fatty acid, and inflammatory cytokine profiles similar to that of IBD patients." (PMID 35479093, 2022). "Compared with CON, the number of goblet cells, and MUC2 mRNA expression in jejunum of ducks with DSS-induced intestinal inflammation did not significantly differ (P > 0.05), but the concentrations of MUC2 was significantly decreased (P < 0.05)." (PMID 38243258, 2024).
polyp (6 papers, 2010 to 2023). A usually exophytic mass attached to the underlying tissue by a broad base or a thin stalk. "In adjacent normal colon, MUC2 expression was observed solely in the goblet cells, while in the polyp lesions, it was expressed in both the goblet cells as well as the in cytoplasm of crypt epithelial cells." (PMID 27705923, 2017). "Using the model with the negative log-log link to build the ordinal regression, the grade of glandular dysplasia was found to be significantly associated with the three variables of expression levels of MUC1 and MUC2, and polyp site." (PMID 20929551, 2010). "Then, the mucosal immune responses of the infected colons were evaluated in relation to polyp formation through immunostaining to identify mucus MUC2 and determine mucosal immune cell (goblet, lymphocyte and mast) counts, secretory IgA levels and parasitic intestinal invasion." (PMID 36380160, 2023). "MUC2 showed weak immunostaining in 44.5% of the infected colons, and 38.9% were polyp inducers." (PMID 36380160, 2023). "Considering the high clinical utility of the appropriate polyp classification, in this study, we evaluated the potential of colonic mucins (MUC1, MUC4, MUC17, MUC2, MUC5AC, and MUC6) and associated glycans (Tn/STn-MUC1 and CA19-9) for differentiating SSA/P from HP and TA." (PMID 27705923, 2017). "On the other hand, surface epithelium in the lower side of the polyp still preserved intestinal nature, containing CDX2-positive nuclei and MUC2-positive goblet cells." (PMID 24422755, 2014). "A total of 454 polyp specimens comprising 36 hyperplastic polyps, 15 serrated adenomas, 258 tubular adenomas, 114 tubulovillous adenomas, and 31 villous adenomas were included in this study, and were immunostained for MUC1, MUC2, MUC5AC and MUC6 by using mucin specific antibodies." (PMID 20929551, 2010). "Regression analysis, with covariates of gender, age, polyp site, and MUC status included, indicated that negative staining for MUC2, Positive staining for MUC6, and left-sidedness would increase the risk of mucosal or muscularis mucosae invasion in colorectal polyps significantly." (PMID 20929551, 2010).
tubular adenocarcinoma (6 papers, 2013 to 2023). An infiltrating adenocarcinoma in which the malignant cells form tubular structures. "Frequent expression of MUC1 has been associated with the development of tubular adenocarcinoma, while MUC2 expression indicative of the presence of the intestinal metaplasia, which is frequently observed in IPNB lineage." (PMID 37721561, 2023). "The superficial part was well-differentiated tubular adenocarcinoma, expressed the intestinal type of MUC2." (PMID 34032698, 2021). "Carcinogenesis via BilIN, predominantly associated with tubular adenocarcinoma, is characterized by a negative expression of MUC2 and an increase in the expression of MUC1, indicating the MUC1-positive pathway." (PMID 37721561, 2023). "The phenotype of PGC-/MUC1-/MUC2+ may be a predictive biomarker for diagnosing MA or SRCC or distinguishing from tubular adenocarcinoma accompanied by mucinous secretion or signet ring cell scattered distribution." (PMID 23937908, 2013). "The phenotype of PGC-/MUC1-/MUC2+ may be a predictive biomarker for diagnosing MA or SRCC, or distinguishing histological MA or SRCC from tubular adenocarcinoma accompanied by mucinous secretion or signet ring cell scattered distribution." (PMID 23937908, 2013). "Probably no because it was not specific since part of the MUC2+ phenotype of GC belongs to tubular adenocarcinoma." (PMID 23937908, 2013).
amebiasis (5 papers, 2016 to 2024). A parasitic infectious disorder caused by amoebas. "Furthermore, it was shown that EhCP-A5 abrogates the MUC2 protective function by cleavage of the MUC2 C-terminus and that EhCP-A5 also plays an role in contact-dependent mucin hypersecretion during intestinal amebiasis." (PMID 27575775, 2016). "Thus, in addition to cleaving the C-terminus of MUC2 to abrogate MUC2 protective functions, EhCP5 plays an essential role in contact-dependent mucin hypersecretion during the pathogenesis of intestinal amebiasis." (PMID 27073869, 2016). "Interestingly, MUC2 plays a vital role in the development and progression of amebiasis." (PMID 33013869, 2020). "In addition to MUC2 degradation, altered MUC2 production is found in intestinal amebiasis." (PMID 33013869, 2020). "Within the biological process of amoebiasis, dietary supplementation with PPAH decreased the expression of several genes, including Il6, Serpinb9c, Rab5a, Muc2, Rab7, Lamb1, and Lama1." (PMID 39591294, 2024).
Constipation (5 papers, 2019 to 2025). Infrequent or difficult evacuation of feces. "Consistent with that, the subjects recruited in this study all had symptoms of constipation, the SNVs identified in the samples were enriched in the genes associated with gut functions, e.g. the mucin gene (MUC2, MUC3A, MUC4, and MUC5B)." (PMID 33412999, 2021). "Postbiotics derived from Lactobacillus paracasei enhance the mucin-2 (MUC2) expression in murine models of constipation, thus supporting the maintenance and repairing of IEB." (PMID 40507435, 2025). "The decreased MUC2 expression levels reduced the release of mucins, suggesting that constipation-induced dysbiosis results in a compromised epithelial barrier." (PMID 36145079, 2022). "A recent study demonstrated that mice colonized with microbiota from patients with constipation had abnormal defecation parameters and decreased MUC2 expression levels." (PMID 36145079, 2022).
diabetes (5 papers, 2022 to 2024). "Moreover, the authors showed that the changes in the mucosal barrier, including a reduction in the number of Goblet cells and impairment in MUC2 production, precede the onset of diabetes in NOD mice." (PMID 37110604, 2023). "Only Muc2 was significantly reduced in the colon in the B. fragilis group before adjusting for multiple testing, and hence, we could conclude that improved gut barrier function was not involved in the reduced diabetes incidence." (PMID 39136533, 2024).
E. coli infection (5 papers, 2021 to 2025). "Studies indicated that Pediococcus pentosaceus IM96 remitting E. coli infection leads to intestinal mucosa damage in mice and inflammatory cell infiltration of an increased level of MUC-2 and TJ proteins." (PMID 40151573, 2025). "Our results showed that after E. coli infection, MUC2 protein was significantly down-regulated, weakening intestinal adhesion and pathogen resistance." (PMID 38390621, 2024). "Regarding E. coli infection, the lower expression levels of MUC-2 and FABP-2 genes in infected and untreated birds were associated with excessive gut inflammation." (PMID 35812892, 2022). "E. coli infection decreased the expression of ZO-1, occludin, and MUC2, while MPX treatment significantly increased their expression in the jejunum and colon; this effect of MPX was superior to that of Enro (p < 0.05)." (PMID 34177825, 2021). "Escherichia coli infection reduced the expression of ZO-1, occludin, and MUC2 in the mouse jejunum and colon, while the expression of ZO-1, occludin, and MUC2 was improved after treatment with MPX." (PMID 34177825, 2021). "Immunofluorescence was used to further study the effect of MPX on TJ protein and MUC2 expression after E. coli infection." (PMID 34177825, 2021). "Here, we show that MUC2 is upregulated by MAP infection, a normal response to an intestinal pathogen as seen with E. coli infection." (PMID 39170608, 2024).
intraductal papillary mucinous neoplasm (5 papers, 2016 to 2025). "It was shown that the intestinal subtype of IPNB was more frequently positive for MUC1 and less frequently positive for MUC2, MUC5AC and CDX2 (a MUC2 regulating transcription factor), compared to each subtype of pancreatic IPMN." (PMID 30875782, 2019). "We selected MUC1, MUC2, and MUC5AC for further investigation because they were routinely stained in the postoperative pathological reports of FUSCC for antidiastole and grading of intraductal papillary mucinous neoplasms." (PMID 35910854, 2022). "A previous study showed that analysis of DNA methylation status in promoters of MUC1, MUC2 and MUC4 (MSE analysis of pancreatic juice samples) could distinguish between gastric type intraductal papillary mucinous neoplasm (IPMN), intestinal type IPMN, other type IPMN and PDAC." (PMID 27283771, 2016).
parasitic infection (5 papers, 2018 to 2022). "MUC2 is included into gel-forming mucins containing proteins with a structural, antimicrobial, and regulatory function which have been identified to be present during parasitic infection." (PMID 36676016, 2022). "By utilizing Muc2 deficient mice and mice that are resistant (C57Bl/6) or susceptible (AKR) to Trichuris muris infection, studies have illustrated Muc2 mucin is an important component of innate defense in this model of parasite infection." (PMID 30764829, 2019).